FBXO39 (F-box protein 39)
Description:
Substrate-recognition component of the SCF (SKP1-CUL1-F-box protein)-type E3 ubiquitin ligase complex.
Synonyms: FBX39; MGC35179; CT144; FBOX39
Tractability: No criterion of Open Targets' tractability assessment is met for any kind of drug.
Gene: Protein-coding gene on chromosome 17 (6,776,215 to 6,797,101, forward strand). Ensembl gene ENSG00000177294.
Gene Ontology:
Molecular function: protein binding
Biological process: SCF-dependent proteasomal ubiquitin-dependent protein catabolic process
Cellular component: SCF ubiquitin ligase complex
Genetic constraint (gnomAD): Loss-of-function variants: 22 observed, 38.36 expected, observed/expected ratio (o/e) 0.57, 90% interval 0.41 to 0.82. The upper end of that interval is the gene's LOEUF score, 0.82, which puts it in group 3 of 6, group 1 being the genes least tolerant of losing a copy. Missense variants: 536 observed, 570.03 expected, observed/expected ratio (o/e) 0.94, 90% interval 0.88 to 1.01. Synonymous variants: 206 observed, 215.71 expected, observed/expected ratio (o/e) 0.95, 90% interval 0.85 to 1.07.
Homologues: Orthologues: chimpanzee FBXO39 (99% identical), macaque FBXO39 (93% identical), pig FBXO39 (88% identical), rat Fbxo39 (86% identical), dog FBXO39 (86% identical), guinea pig FBXO39 (84% identical), mouse Fbxo39 (84% identical), rabbit FBXO39 (84% identical). Paralogues in human: FBXO31 (15% identical).
Diseases named in the same sentence as FBXO39 in open-access papers:
FBXO39 is named in the same sentence as 15 diseases in open-access papers, as found by Europe PMC text mining. Sharing a sentence is not in itself a finding about the gene and the disease. The quoted sentences say what the papers report.
colorectal cancer (2 papers, 2016 to 2025). A primary or metastatic malignant neoplasm that affects the colon or rectum. "In colorectal cancer, CTAs such as DKKL1, FBXO39, and OIP5 hold great promise as therapeutic targets due to their overexpression and immunogenic properties." (PMID 40599850, 2025). "This study leveraged computational immuno-informatics tools to identify high-affinity HLA class I-restricted epitopes from DKKL1, FBXO39, and OIP5, providing a basis for the development of a peptide-based vaccine for colorectal cancer immunotherapy." (PMID 40599850, 2025). "In view of this, the present study aims to identify lead CTL epitopes targeting DKKL1, FBXO39, and OIP5 CTAs for colorectal cancer." (PMID 40599850, 2025). "This study identified CTL-specific epitopes from DKKL1, FBXO39, and OIP5 as potential targets for colorectal cancer immunotherapy." (PMID 40599850, 2025).
glioma (2 papers, 2025). A benign or malignant brain and spinal cord tumor that arises from glial cells (astrocytes, oligodendrocytes, ependymal cells). "They documented that overexpression of FBXO39 is positively correlated with the diagnostic grade of glioma and negatively associated with patient survival rate." (PMID 40504854, 2025). "Among the seven key genes (HOXD11, HOXC9, HOXC6, HOXA3, FBXO39, OTP, and HMGA2) consistently detectable in both normal astrocyte cell lines (SVG-P12) and glioma cell lines (U87, U251, LN229), tumor cell lines exhibited significantly upregulated expression compared to normal cell lines." (PMID 41049291, 2025).
cervical squamous cell carcinoma (1 paper, 2025). A squamous cell carcinoma arising from the cervical epithelium. "Published research showed that FBXO39 cancer/testis antigen was considered a promising biomarker for the prognosis of cervical squamous cell carcinoma, breast, colon, and glioma cancer." (PMID 40504854, 2025).
male infertility (1 paper, 2026). The inability of the male to effect fertilization of an ovum after a specified period of unprotected intercourse. "Further analyses of FBXO39 may contribute to understanding the etiology of male infertility." (PMID 41916926, 2026).
Obesity (1 paper, 2016). Accumulation of substantial excess body fat. "Moreover, two tested CTAs were significantly downregulated in smoking patients (MAGEA1, AE; FBXO39, AE and RE) and one CTA (LDHC) seemed to be upregulated (AE) in patients with obesity." (PMID 27635108, 2016).
tumor (4 papers, 2016 to 2025). "Using tumor samples from our cohort of 29 patients and an RT-qPCR approach, we found that FBXO39 and CEP55 genes were highly expressed in GBM and that their expression predicted the OS (P < 0.05)." (PMID 40504854, 2025). "FBXO39, an F-box protein family member, contributes to tumor cell survival by regulating proteasomal degradation pathways and has been implicated in promoting colorectal tumor progression and drug resistance." (PMID 40599850, 2025). "When the Wilcoxon signed-rank test was used, we noted that 6 of 18 (33%) CTAs tested, MAGEA3, OIP5, TTK, PLU1, DKKL1, and FBXO39, were significantly (p < 0.05) overexpressed in the tumor compared with normal tissue located ~5 cm away from the primary lesion." (PMID 27635108, 2016). "In contrast to neoantigen-based vaccines, which focus on targeting mutation-specific antigens unique to individual tumors, our multi-epitope vaccine targets conserved tumor-associated antigens (DKKL1, FBXO39, and OIP5) that are widely expressed across CRC patients." (PMID 40599850, 2025). "In this study, we identified a significant increase in FBXO39 and CEP55 expression in GBM tumor tissues compared to normal brains by wet bench as well as by bioinformatic pubic data analyses." (PMID 40504854, 2025). "To validate our finding on the prognostic value of FBXO39 and CEP55 gene expression, we prepared RNA from our tumor samples of 29 patients." (PMID 40504854, 2025). "Among these CTAs: DKKL1, FBXO39, and OIP5 have emerged as particularly attractive targets for immunotherapy due to their specific overexpression in tumor tissues and roles in promoting oncogenesis." (PMID 40599850, 2025).
cancer (3 papers, 2016 to 2025). A tumor composed of atypical neoplastic, often pleomorphic cells that invade other tissues. "FBXO39, part of the F-box protein family, is involved in tumorigenesis and has been associated with the development and progression of multiple cancers, including CRC." (PMID 40599850, 2025). "Compared to these efforts, our study uniquely focuses on the cancer-testis antigens DKKL1, FBXO39, and OIP5, which have been largely underexplored in CRC immunotherapy despite their selective overexpression and potent immunogenic potential." (PMID 40599850, 2025).
FBXO39 also shares sentences with these, for which no sentence is quoted: infection (3 papers); breast carcinoma (1); esophageal squamous cell carcinoma (1); head and neck squamous cell carcinoma (1); lung carcinoma (1); melanoma (1); multiple myeloma (1); proctitis (1).